RNU6-388P (RNA, U6 small nuclear 388, pseudogene)
Gene: Small nuclear RNA gene on chromosome 7 (33,001,950 to 33,002,054, reverse strand). Ensembl gene ENSG00000252821.
Homologues: Orthologues: chimpanzee U6 (99% identical), macaque U6 (94% identical), pig U6 (73% identical). Paralogues in human: RNU6-389P (98% identical), RNU6-175P (81% identical), RNU6-1249P (78% identical), RNU6-43P (78% identical), RNU6-536P (78% identical), RNU6-727P (78% identical), RNU6-1047P (77% identical), RNU6-115P (77% identical), RNU6-454P (77% identical), RNU6-652P (77% identical), RNU6-668P (77% identical), RNU6-108P (76% identical), and 1287 more.